CRP (C-reactive protein)
Diseases named in the same sentence as CRP in open-access papers (continued):
Sharing a sentence is not in itself a finding about the gene and the disease.
ischemic stroke (continued). "A study of pooled cohort from the Dallas Heart study (DHS) and Multi-Ethnic Study of Atherosclerosis (MESA) demonstrated differential association of GlycA and Hs-CRP with CVD; GlycA strongly predicted incident of myocardial infraction, and Hs-CR strongly predicted ischemic stroke." (PMID 36675414, 2023). "Among the 63,492 identified elderly patients (mean age 78.0 ± 8.1 years, 51% females) with available CRP measurement within 24 h after the ischemic stroke, 9,249 (16.2%) had CRP levels < 1 mg/L, 12,586 (20.6%) CRP levels of 1–3 mg/L, and 41,657 (63.2%) CRP levels of > 3 mg/L." (PMID 37119383, 2023). "The presence of elevated CRP among patients with ischemic stroke could be attributed to the presence of concomitant infections." (PMID 37119383, 2023). "Therefore, the relationship between plasma CRP values and functional outcomes after ischemic stroke during the regenerative-compensatory period should be further validated in other cohorts." (PMID 36769677, 2023). "The initial cohort consisted of 104,741 patients with ischemic stroke (mean age 65.8 ± 16.4, 51.4% female) and CRP measured during the first 24 h from the index event from 65 (primarily United States) health care organization with mean age of 65.8 ± 16.4 (51.4% female)." (PMID 37119383, 2023). "CRP and PCT levels, and OASIS were identified as the main risk factors for patients with ischemic stroke complicated by SAP, thus indicating that the onset of SAP is significantly affected by the patient's age, body temperature at admission, CRP and PCT levels, and OASIS." (PMID 37731859, 2023). "Other studies relating CRP levels to ischemic stroke have shown contrary results." (PMID 35399841, 2022). "A meta-analysis illustrated that elevated baseline hs-CRP levels were independently associated with excessive ischemic stroke risk but exhibited no clear effect on hemorrhagic stroke." (PMID 36056376, 2022). "Other researchers found that in the general population, elevated plasma YKL-40 levels are associated with increased risk of ischemic stroke and ischemic cerebrovascular disease, independent of plasma CRP levels." (PMID 35625766, 2022). "A considerable proportion (66%) of the included patients had hs-CRP ≥2 mg/L in association with an increased risk of major adverse cardiovascular events (a composite endpoint of nonfatal MI, nonfatal ischemic stroke or cardiovascular death)." (PMID 36556477, 2022). "CRP in ischemic tissues drives the progression of AD following ischemic stroke." (PMID 35054785, 2022). "CRP concentration was first found to be an independent predictor of survival after ischemic stroke." (PMID 36703636, 2022). "LPS and CRP levels were elevated in ischemic strokes (CE, LAA, SVO) and ICH compared to controls." (PMID 33753837, 2021). "Furthermore, in a case-control study, serum CRP level in patients with all ischemic stroke subtypes were significantly higher in both the acute phase and at 3-month follow-up." (PMID 33967939, 2021). "While ISR was associated with the occurrence of recurrent ischemic stroke (p = 0.003), CRP, NLR, PLR and MPV were not predictive of such events (p > 0.1)." (PMID 34341413, 2021). "In ischemic stroke patients, the elevation of CRP was also correlated with a bad prognosis." (PMID 34712729, 2021). "The study indicated that NLR was more predictive of ischemic stroke than C-reactive protein, suggesting that NLR and C-reactive protein may represent different biological aspects of inflammation." (PMID 33958997, 2021). "A growing body of research suggests that CRP may be an inflammatory factor in response to ischemic stroke." (PMID 34212039, 2021). "Applying CRP apheresis in ischemic stroke is the next plausible step." (PMID 32932587, 2020). "However, the role of CRP in predicting the survival outcome amongst ischemic stroke remains controversial." (PMID 30718369, 2019).
ischemic stroke (continued). "Elevated baseline higher CRP level could predict an unfavorable long-term functional outcome in patients with ischemic stroke." (PMID 30718369, 2019). "Previous meta-analysis only evaluated the association between CRP elevation and poor functional outcome but did not focus on the all-cause mortality outcome in patients with ischemic stroke." (PMID 30718369, 2019). "It has been shown that CRP has at least as strong an association with delirium after ischemic stroke as NLR, but it is not always available to the clinician." (PMID 31336587, 2019). "Fourth, we did not measure other biomarkers such as high-sensitivity C-reactive protein, which is associated with the risk of ischemic stroke and vascular events." (PMID 29789903, 2018). "Hs-CRP was associated with MI and ischemic stroke independent of other traditional atherosclerotic risk factors." (PMID 31249941, 2018). "Table 2displays IRs and HRs for MI and ischemic stroke across quintiles of hs-CRP." (PMID 31249941, 2018). "It has been described that blood levels of high-sensitivity CRP (HS-CRP) may be considered an independent predictor for ischemic stroke, although the exact correlation remains unclear." (PMID 28209139, 2017). "For instance, elevated C-reactive protein (CRP), a well-studied marker for chronic inflammation, has been shown to be an independent risk factor for both coronary heart disease (CHD) and ischemic stroke events, and has been suggested to be implemented in risk prediction models." (PMID 28829826, 2017). "This tentatively suggests that NLR may go beyond being a collinear counterpart of CRP, reflecting different biological aspects of inflammation that may have higher predictive value for ischemic stroke." (PMID 28829826, 2017). "The first involves exacerbation of brain infarction, as CRP itself may worsen clinical outcomes after ischemic stroke." (PMID 27258004, 2016). "According to the findings of the current study, higher CRP levels not WBC on admission in acute ischemic stroke patients are associated with poor outcome." (PMID 27757207, 2016). "Thus, our preliminary results further supported the independent contribution of HNF1A and CRP to ischemic stroke." (PMID 27460564, 2016). "Therefore, it is not possible to estimate ischemic stroke reduction from statin use in any other strategy evaluated in our model since we would be unable to establish a baseline risk of ischemic stroke based on a person’s initial FRS, CAC score, or CRP level." (PMID 26422204, 2015). "CRP is an independent predictor of long-term mortality after ischemic stroke." (PMID 19400931, 2009). "Thus, studies have demonstrated that a panel of biomarkers, including complement C3, high-sensitive C-reactive protein, hepatocyte growth factor, MMP9, and anti-phosphatidylserine antibodies, can provide more comprehensive risk stratification for adverse outcomes in ischemic stroke." (PMID 39459548, 2024). "This study showed that despite demonstrating a significant relationship between CRP levels and corresponding mRS scores, CRP levels alone may not serve as an independent predictor of long-term functional outcomes in ischemic stroke patients undergoing rehabilitation." (PMID 36769677, 2023). "Our thorough study revealed that the CRP gene variants rs1800947, rs1130864, rs3093059, rs2794521, and rs1205 could not be related to the risk of ischemic stroke." (PMID 37221147, 2023). "Elegantly, this could potentially be achieved through intensified statin use, as one of the lipid-lowering agent properties is to dose-dependently reduce levels of not only LDL—known to also negatively impact the prognosis of ischemic stroke patients—but also CRP and other inflammatory markers." (PMID 37360331, 2023). "However, another study reported that genetically elevated IL-1Ra, soluble IL-6 receptor (sIL-6R), and C-reactive protein (CRP) levels are not causally associated with ischemic stroke." (PMID 35111052, 2021).
ischemic stroke (continued). "Furthermore, studies have revealed that CRP could also be potentially used to predict impending atherosclerotic-related diseases, including ischemic stroke and cardiovascular disorders." (PMID 34489618, 2021). "Thus, Lp‐PLA2 may be a more useful biomarker than hs‐CRP for evaluating the prognosis of ischemic stroke in patients with H‐type hypertension." (PMID 31630457, 2020). "Furthermore, the prognostic role of CRP may also be affected by different phases or subtypes of ischemic stroke." (PMID 30718369, 2019). "Conflicting evidences suggested CRP may be a prognostic biomarker of ischemic stroke outcome." (PMID 30294205, 2018). "Additionally, the CRP 1444 (CC/CT vs. TT) polymorphism was associated with plasma levels of CRP but not with ischemic stroke or ICH." (PMID 30254628, 2018). "Furthermore, high CRP levels in the acute phase of ischemic stroke can predict adverse outcomes." (PMID 29245986, 2017). "Furthermore, a very recent study reported how therapy with statins, either previous or early initiation, after an ischemic stroke, could improve the survival and readmission rates by lowering both cholesterol and high-sensitivity C-reactive protein levels." (PMID 27043681, 2016). "Therefore, genes affecting CRP level seem to be promising candidate genes of ischemic stroke." (PMID 27460564, 2016). "PCT is more accurate than CRP in diagnosing infections, especially sepsis and studies have identified associations between PCT and poor outcome or death in patients with alterations of the central nervous system, such as ischemic stroke and postanoxic encephalopathy." (PMID 26450065, 2015). "However, although several biomarkers are inferior to CRP in patients with ischemic stroke, studies on other markers may be of importance to characterize the network of mediators that are involved in the development of this complex disorder." (PMID 22174896, 2011). "Our study identified significant predictors of END in ischemic stroke patients, including alcohol and tobacco use, higher initial NIHSS scores, and elevated levels of LDH, ferritin, ESR, CRP, and homocysteine, along with low vitamin B12 levels." (PMID 39347249, 2024). "This study aims to investigate the biochemical predictors of END in patients with ischemic stroke, focusing on markers such as LDH, ferritin, ESR, CRP, homocysteine, and vitamin B12." (PMID 39347249, 2024). "For ischemic stroke, severe decreased rCVR findings on Diamox SPECT (HR: 5.939, CI 1.616–21.829, P < 0.01) and increased CRP levels (HR: 1.465, CI 1.009–2.127, P = 0.05) were significantly associated with end-point events." (PMID 38167529, 2024). "The NIHSS score, the mRS score after 90 days and the levels of NLRP1, CRP, TNF-α IL-6 and IL-1β of ischemic stroke patients in the ASITN/SIR grade 0 to 2 group were remarkably elevated than the ischemic stroke patients in ASITN/SIR grade 3 to 4 group." (PMID 37000063, 2023). "An increase in systemic inflammatory agents such as IL-1β, IL-6, and C-reactive protein (CRP) plays the most important roles in the genesis of neuroinflammation in CSVD and ischemic stroke." (PMID 36676165, 2023). "To further investigate the relationship between NLRP1 and inflammatory factors in ischemic stroke patients, we measured the serum levels of NLRP1, CRP, IL-6, TNF-α, and IL-1β by ELISA." (PMID 37000063, 2023). "As reported recently in a clinical study, NBP combination with Edaravone treatment significantly decreased serum Tumor necrosis factor-α (TNF- α), C-reactive protein (CRP), and Interleukin-6 (IL-6) levels of ischemic stroke patients." (PMID 37243759, 2023). "- History of drinking, increased levels of homocysteine (HCY) and highly sensitive C-reactive protein (hs-CRP), and ST changes in ECG were more likely occurred in the patients with ischemic stroke." (PMID 35345487, 2022). "Facing progressive ischemic strokes and vessel stenoses we decided to start a steroid treatment suspecting GCA under which BSR and CRP decreased." (PMID 35112048, 2022).
ischemic stroke (continued). "We could not demonstrate the causal relationship of hs-CRP and ischemic stroke in NAFLD patients." (PMID 35399841, 2022). "Compared with patients with MoCA >22, the patients with MoCA ≤ 22 were older, had lower level of education, higher proportions of previous ischemic stroke, large-artery atherosclerosis (LAA) subtype, and multiple infarctions, and higher NIHSS and CRP levels." (PMID 34925208, 2021). "Age, hospitalization duration, PHQ-9 scores, MMSE-K scores, hs-CRP, ESR, and AST were adjusted as confounding factors in patients with ischemic stroke." (PMID 34828631, 2021). "CRP apheresis aims to remove circulating CRP after AMI and ischemic stroke in order to reduce acute tissue injury and ischemic reperfusion injury." (PMID 32932587, 2020). "The infection markers and inflammatory molecules, such as CRP, WBC, and IL‐6 were suggested to be biomarkers for outcome of ischemic stroke." (PMID 32196744, 2020). "Serum levels of CRP, IL-6, IL-10, and IL-23 were significantly correlated with lesion volume and/or NIHSS in patients with ischemic stroke." (PMID 27682880, 2017). "On days 0, 3, 7, and 14 after admission, 180 patients with ischemic stroke underwent serial determinations of bilirubin, GOT, GPT, γGT, alkaline phosphatase, C-reactive protein (CRP) and complete blood count." (PMID 24903748, 2014). "Hemoglobin, platelet count, fibrinogen, D-dimers and CRP as well as demographic and clinical characteristics were compared between patients with ischemic stroke and active cancer versus those without known cancer." (PMID 40008556, 2025). "This study aimed to investigate the association between specific biomarkers (lactate dehydrogenase (LDH), ferritin, erythrocyte sedimentation rate (ESR), C-reactive protein (CRP), homocysteine) and the occurrence of END in ischemic stroke patients in a tertiary care hospital." (PMID 39347249, 2024). "The neutrophil-to-lymphocyte ratio (NLR), C-reactive protein (CRP), and serum ferritin have all been found to significantly rise in patients with ischemic stroke, suggesting that these patients’ mortality may be predicted." (PMID 36979225, 2023). "As downstream biomarkers of IL-1 induction, elevated plasma levels of C-reactive protein (CRP) and IL-6 may be predictive of poor clinical outcome in the acute phase of ischemic stroke." (PMID 37119383, 2023). "In 130 patients with acute focal neurologic deficits admitted within 6 h of onset of symptoms, a panel including D-dimer, CRP, B-type natriuretic protein (BNP), MMP-9, and S100B was predictive of ischemic stroke with sensitivity and specificity of 81 and 70%, respectively." (PMID 33633673, 2021). "NSE and CRP were increased in acute stroke compared to control, but were not statistically different between ischemic stroke and ICH." (PMID 33115334, 2021). "Indeed, our results show CRP levels increase proportional to LPS levels in controls, TIA, ischemic stroke and ICH subjects, and the correlation coefficient is 0.90 (p < 0.00001) with the trendline for LPS vs CRP intercepting near zero on both axes." (PMID 33753837, 2021). "Studies have shown that increased IL-18 level contributed to the development of ischemic stroke, and nonspecific inflammatory factors, such as hypersensitivity C-reactive protein and ESR, are elevated in the high RDW group." (PMID 32445553, 2020). "Higher levels of CRP (C-reactive protein), but not interleukin-6 (IL-6) or the CRP level relative to that of IL-6, were associated with increased risk of ischemic stroke in population-based studies." (PMID 30999680, 2019). "In conclusion, we found that the association between RDW and arterial CVD was not confounded by hs-CRP, and that RDW had a modest direct effect on the risk of ischemic stroke, but not MI." (PMID 31249941, 2018).
ischemic stroke (continued). "In a multivariate model including traditional risk factors, CRP was significantly associated with the risk of having a first ischemic but not ICH [OR for the highest CRP group: 2.58 (1.74–3.84) for ischemic stroke and 0.97 (0.30–3.11) for ICH]." (PMID 30254628, 2018). "Similar to the present study, Canova et al8 and Modrego et al12 failed to conclude any relationship between CRP and outcome of acute cerebrovascular events such as ischemic stroke." (PMID 24353532, 2013). "However, CPR has been found to have high predictive value in predicting infections, solid tumors, and ischemic stroke, which may be related to the property that PCT is elevated in infectious diseases more often than CRP." (PMID 38434730, 2024). "In the clinical part of this study, the quantitative analysis demonstrated circulating TMEM166, interleukin 6 (IL-6), and C-reactive protein (CRP) levels were significantly elevated in patients who suffered an ischemic stroke after CEA compared to those who did not." (PMID 37611898, 2024). "C-reactive protein and NLR have recently been reported as potential novel biomarkers of the baseline inflammatory process and could serve as outstanding predictors in patients with ischemic stroke." (PMID 36010292, 2022). "A systematic review and meta-analysis of 54 long-term prospective studies involving 160,309 CVD-free participants found that increases in CRP were significantly associated with incident IHD, ischaemic stroke and mortality from both vascular and non-vascular causes." (PMID 33567509, 2021). "Moreover, the increase in serum CRP concentrations results in increased risk ratios for CHD, ischemic stroke, vascular mortality, and non-vascular mortality." (PMID 33092652, 2020). "A previous meta-analysis including 160,309 people without a history of vascular disease suggested that CRP concentration has continuous associations with the risk of CAD, ischemic stroke, vascular mortality, and death from several cancers and lung diseases that are each of broadly similar size." (PMID 29338684, 2018). "However, external validation of these finding with prospective studies are pending, and the predictive value of CRP for outcome after ischemic stroke remains controversial, as other studies did not confirm these associations." (PMID 26450065, 2015). "Finally, the AUC values of LGI, CRP, WBC, NLR, and PLT for predicting poor outcomes on day 90 were 0.682, 0.6533, 0.6258, 0.6712, and 0.52, respectively, indicating that the LGI score is more superior to other single indicators in predicting outcomes of ischemic stroke patients." (PMID 37679730, 2023). "For example, some of the differentiation proteins, such as SERPINA3 and CRP involved in inflammatory/acute-phase response, as well as FGA and PLG involved in blood coagulation, were associated with the cardioembolic, large-vessel, and lacunar ischemic stroke subtypes, but not with CBS deficiency." (PMID 31242583, 2019). "Finally, elevated CRP level after thrombolysis treatment did not independently predict the outcome in patients with ischemic stroke, suggesting that tissue plasminogen activator may influence the prognostic significance of CRP." (PMID 30718369, 2019). "However, the role of CRP in the pathogenesis of ischemic stroke is not completely understood." (PMID 22132330, 2011). "Interestingly, subcutaneous IL-1Ra application in ischemic stroke patients within 5 h of symptom onset in the SCIL-STROKE Phase 2 trial also observed a reduction of IL-6 and CRP after treatment without reporting any safety concerns." (PMID 37212886, 2023). "There was evidence of genetic correlation between critical Covid-19 and ischemic stroke (rg=0.29, FDR p-value=4.65×10−3), body mass index (rg=0.21, FDR-p-value=6.26×10−6) and C-reactive protein (rg=0.20, FDR-p-value=1.35×10−4), but none of the other considered traits." (PMID 33688662, 2021).